NDRG1 (N-myc downstream regulated 1)
Diseases named in the same sentence as NDRG1 in open-access papers (continued):
Sharing a sentence is not in itself a finding about the gene and the disease.
cancer (continued). "This suggests a potential role for NDRG1 in these cancers, particularly those influenced by hormones." (PMID 38987777, 2024). "It is evident from our data that nuclear NDRG1 is an important consideration moving forward to further understand NDRG1's role in breast and other cancer progression." (PMID 40530439, 2024). "Metastasis is the major killer in cancer and NDRG1 is a potent metastasis suppressor in multiple cancers." (PMID 38815861, 2024). "Recent articles have reported abnormal expression of NDRG1 in various cancers, and the expression levels of this gene in different tumors are not completely consistent, even showing opposite tumorigenic effects in different tumors." (PMID 39668822, 2024). "NDRG1 has been variably reported as a metastasis suppressor, a biomarker of poor outcome and a facilitator of disease progression in many cancers." (PMID 40530439, 2024). "When viewed together, these studies show that NDRG1 has at least two roles in ccRCC: it inhibits cancer cell proliferation, and when phosphorylated, it inhibits apoptosis." (PMID 37298315, 2023). "Hypoxia-induced overexpression of NDRG1 is recognized as a prognostic biomarker in various human cancers." (PMID 37047450, 2023). "It was recently reported in cancer cells the existence of two NDRG1 isoforms, at ~47kDa and ~46kDa, which correlated with phosphorylation at Thr346 and Ser330, respectively." (PMID 36594086, 2023). "Up-regulation of NDRG1 using the novel clinically trialed anti-cancer agent DpC effectively inhibited PaC growth and metastasis in vivo, while also reducing activation of PSCs and inhibiting ECM production." (PMID 37345116, 2023). "In fact, NDRG1 was found to influence the secretome of PaC cells, alter cancer cell metabolism, and interfere with intracellular trafficking and intercellular communication between PaC cells and surrounding fibroblasts." (PMID 37345116, 2023). "The induction of NDRG1 in response to hypoxia in cancer cells inhibits apoptosis and thus promotes cancer cell survival in tumors that have high levels of hypoxia." (PMID 37298315, 2023). "Iron chelators, such as Dp44mT and DpC, which exhibit selective antitumor activity were shown to upregulate NDRG1 and inhibit stress-induced autophagy in cancer cells." (PMID 37847564, 2023). "These contrasting results suggest that the function of NDRG1 is heavily context-dependent, and further research is required to elucidate how its function is influenced in different cancer types and under different physiological conditions." (PMID 37345116, 2023). "For an in-depth review of NDRG1, its structure, and functions in cancer and other diseases, we refer the reader to excellent recent reviews on this protein." (PMID 37345116, 2023). "NDRG1 processing in cancer cells includes proteasome-dependent processing of the ~47kDa isoform into the ~46kDa isoform that is further degraded by the lysosomal compartment." (PMID 36594086, 2023). "Recently, studies reported that NDRG1 can suppress tumorigenesis by limiting and regulating the cancer TME." (PMID 37345116, 2023). "Considering that the phosphorylation of primary mTORC1 downstream targets was not different in ccRCC samples relative to pair-matched normal renal tissue, we focused on the regulation of NDRG1 phosphorylation on Thr346 in ccRCC cancer cells." (PMID 37298315, 2023). "It has been well documented that NDRG1 can disrupt TGF-β-induced epithelial-to-mesenchymal transition (EMT) in cancer cells." (PMID 37345116, 2023). "NDRG1 was overexpressed in tumors (p < 0.001), supporting the oncogenic function of this molecule in cancer formation." (PMID 35563887, 2022). "The wide array of roles played by NDRG1 are dependent on post-translational modifications and subcellular localization, as well as the cellular context, for example, cancer type." (PMID 36497221, 2022). "NDRG1 plays a context dependent role in cancers by either suppressing or promoting metastasis, depending on the cancer type." (PMID 36497221, 2022).
cancer (continued). "The use of novel thiosemicarbazone iron chelators as NDRG1 modulators has been explored in both cancer cells and xenograft models." (PMID 36497221, 2022). "As high-risk cancers often abnormally express myc, myc-mediated regulation of NDRG1 makes this protein an interesting therapeutic candidate in cancer." (PMID 36497221, 2022). "Overexpression of NDRG1 significantly promoted cancer stemness in the two HNC cell lines, as observed by the increase in the number and size of the cellular spheres (p < 0.001 in OECM1 cells and p < 0.01 in FaDu cells)." (PMID 35563887, 2022). "These molecular results support the cellular investigations that NDRG1 contributes to cancer stemness with a minor role by its 3R-motif." (PMID 35563887, 2022). "Herein, we will broadly consider the function of NDRG1, as well as its role in different cancer types and metastasis." (PMID 36497221, 2022). "The role of NDRG1 as a metastasis-suppressor protein has been widely reported in different cancers including the colon, prostate, breast, and pancreas." (PMID 36497221, 2022). "NDRG1 also inactivates canonical Wnt/β-catenin signaling in BM stromal progenitor cells and cancer cells, while promoting β-catenin plasma membrane expression." (PMID 36357486, 2022). "We have recently published a review article highlighting iron chelation as capable of reversing several hallmarks of cancer through NDRG1 disrupting oncogenic signaling pathways." (PMID 36213122, 2022). "The metastasis suppressor, N-myc downstream-regulated gene-1 (NDRG1) is able to dampen tumorigenesis by inhibiting these two pathways as well as by decreasing TGFβ production by cancer cells." (PMID 35785162, 2022). "NDRG1 expression was also reported to mediate cancer stem cell differentiation in OS cells via Wnt activation." (PMID 36497221, 2022). "Among all dysregulated genes, N-myc downstream-regulated gene 1 (NDRG1) was overexpressed in cancer tissues to the greatest extent, suggesting a significant role for this molecule in HNC formation." (PMID 35563887, 2022). "This review summarizes the role of NDRG1 in cancer and provides an overview of its expression and function in different cancer types." (PMID 36497221, 2022). "Therapeutic NDRG1 induction mediated by iron-chelators such as DpC and Dp44mT is a promising intervention for cancer suppression." (PMID 36497221, 2022). "Although the role of NDRG1 in various types of cancer remains elusive, the present findings reveal its oncogenic function in HNC." (PMID 35563887, 2022). "We further validated these roles by showing that NDRG1 promotes cancer stemness conversion and contributes to chemo-radioresistance in HNC cells." (PMID 35563887, 2022). "Thus, NDRG1 facilitating cancer metastasis may be the primary cause of cancer progression." (PMID 35563887, 2022). "In this context, iron chelators targeting the modulation of NDRG1 and similar biomolecules involved in the regulation of metastasis can play a major role in inhibiting cancer progression and metastasis and increasing overall cancer patient survival." (PMID 36430469, 2022). "NDRG1 expression is suppressed via metabolic regulators including N-myc, and the locus is hypermethylated in many cancer tissues including gastric, colon, pancreatic, prostate and some breast cancers." (PMID 36357486, 2022). "Last but not least, upregulation of miR-1469-5p is closely associated with cancer cell proliferation and the migratory behavior of PDAC by targeting and regulating the N-Myc Downstream Regulated 1 (NDRG1)/NF-κB/E-cadherin axis." (PMID 36292753, 2022). "This ability was also observed in NDRG1-dC transfectants, suggesting that the 3R-motif of NDRG1 has a negligible effect on cancer stemness." (PMID 35563887, 2022). "Given the diversity of NDRG1’s post translational modifications and subcellular localization, it is not surprising that it has such context dependent functions in cancer progression." (PMID 36497221, 2022).
cancer (continued). "To extend the cellular effect of NDG1 to molecular presentations, we determined the expression of cancer stemness-associated regulators (ABCG2, Twist1, BMI1, NES, c-Met) in NDRG1-FL-transfected HNC cells." (PMID 35563887, 2022). "The potential for pharmacological targeting of NDRG1 in cancer highlights the importance of understanding the role of NDRG1 within adaptive immunity." (PMID 36357486, 2022). "Once NDRG1 was lost, the cancer cells will develop into a more aggressive form with an excessively activated cytoskeleton-reorganization signaling axis." (PMID 33994856, 2021). "NDRG1 is a known metastasis inhibitor in a variety of cancers, participating in embryogenesis, cell growth, lipid biogenesis, stress response, and immunity." (PMID 33912215, 2021). "NDRG2, another member of NDRG family which includes four members NDRG1-4, was reported to be significantly decreased in human cancers, and in GC, H. pylori silenced Ndrg2 by activating the NF-κB pathway and up-regulating DNMT3b, promoting GC progression." (PMID 34616614, 2021). "As is well reported, NDRG1 plays its contradictory role in numerous cancers progression via various signalling pathways." (PMID 34965023, 2021). "N-myc downstream regulated gene-1 (NDRG1) has been identified as a putative metastasis suppressor gene and proved to be a key player in cancer spreading and proliferation in our previous work." (PMID 33994856, 2021). "Combining the essential role of NDRG1 in cancer metastasis inhibition, we sequentially validated its negative correlation with CLDN2 expression as indicated by western blot and Pierson correlation analyses." (PMID 34965023, 2021). "Further analysis of CNV in 8q24.2 at genetic resolution revealed that amplifications of the oncogenes, MYC (p = 0.0001) and NDRG1 (p = 0.0004), located on this fragment were also associated with HRD in a pan-cancer manner." (PMID 34976815, 2021). "NDRG1 pS330 was increased in cases with high Gleason grade (Gleason 4/5) compared with tumors with low Gleason grade (Gleason 3) or non-cancer tissue (p = 0.044)." (PMID 33398037, 2021). "NDRG1 has been proven to be the common link between the ability of iron chelators to reverse many of the hallmarks of cancer as overexpression of NDRG1 mimics the impact of iron chelation on several signalling pathways." (PMID 33520115, 2021). "In mammals, it has been well established that Ndrg1 exerts an inhibitory effect on cancer cell proliferation." (PMID 33646121, 2021). "Further, extensive studies have indicated that NDRG1 is upregulated by iron ions in various cancer cells, resulting in its potent anticancer activity." (PMID 34077484, 2021). "Due to the importance of this protein in the anti-cancer efficacy of these latter drugs, the structure and function of NDRG1 will be described in detail below." (PMID 34572031, 2021). "N-myc downstream regulated gene-1 (NDRG1), identified as a metastasis suppressor recently, has been proven to be a key player in affecting cancer proliferation, spreading, cell adhesion, and autophagy 4-6." (PMID 33994856, 2021). "In sum, these results explain the phenotypic change in cancer cells and indicate an inhibitory role of NDRG1 in actin reorganization and cell invasiveness via a CDC42/PAK1/Cofilin dependent pathway." (PMID 33994856, 2021). "NDRG1 expression is elevated in non-small cell lung carcinoma and contributes to cancer growth while having a variety of functions." (PMID 34142021, 2021). "Further analysis of CNV in 8q24.2 at genetic resolution revealed that amplifications of the oncogenes located on this fragment, MYC and NDRG1, were also associated with HRD in a pan-cancer manner." (PMID 34976815, 2021). "The PIM1 substrates we identified were involved in a variety of oncogenic processes, and included N-Myc Downstream-Regulated Gene 1 (NDRG1), which has reported roles in suppressing cancer cell invasion and metastasis." (PMID 33398037, 2021).
cancer (continued). "We found that NDRG1 was predominantly localized in the cytoplasm, and NDRG1 expression was increased in cancer issues compared with the paired adjacent tissue samples (P < .0001)." (PMID 32537867, 2020). "Taking all these data into account, we identified the following candidates as potential causes of CA in human cancer: gain of function of CEP19, CEP72, CTNNB1, PTK2, NDRG1, SPATC1, TBCCD1; and loss of function of CEP76, MCPH1, NEURL4, NPM1." (PMID 32681070, 2020). "NDRG1 protein was significantly increased in ccRCC cancer tissues compared to paired normal renal tissues." (PMID 32537867, 2020). "In conclusion, we demonstrated HIF downstream gene of NDRG1 counteracts the cancer‐promoting effect of HIF." (PMID 32537867, 2020). "Here we also established the murine xenograft model to validate the anti-cancer role of hsa_circ_0003159 and the regulatory network of hsa_circ_0003159/miR-223-3p/NDRG1 in vivo." (PMID 32099530, 2020). "A high NDRG1 status in carcinoma cells in pre-NAC biopsy specimens was significantly associated with lower NAC effects, and a high GR and Sgk1 status in carcinoma cells tended to be associated with lower NAC effect." (PMID 32106831, 2020). "It has been shown that NDRG-1 was downregulated in majority of cancers and acts as a metastasis suppressor protein in at least a group of human carcinomas." (PMID 31594284, 2019). "We also conducted mutually exclusivity analysis to identify the functional mechanism of NDRG1 in the oncogenesis and progression of the four cancers." (PMID 31205821, 2019). "It has been demonstrated that NDRG1 overexpression inhibits the initiation of basal autophagy and the ER-stress-mediated autophagy pathway in cancer cells." (PMID 31189711, 2019). "N-myc downstream regulated gene 1 (NDRG1) is an intracellular protein involved in cell differentiation and was recently reported to exert various effects in several cancers." (PMID 30914736, 2019). "While convincing evidence supporting a direct role of N-Myc in regulating angiogenesis is scarce, NDRG1 (N-Myc downstream-regulated gene 1) has demonstrated pleiotropic roles in angiogenesis and cancer progression, depending on cancer types." (PMID 32039001, 2019). "A tissue array containing 89 pairs of cancer and matched normal tissues was used to examine the expression of NDRG1 by Immunohistochemistry assay (IHC)." (PMID 31831018, 2019). "NDRG1, which is normally present in human epithelial cells, has regulatory biologic effects on many cancer cells, including bladder and prostate." (PMID 30813460, 2019). "In accordance with the dataset-based analysis, the IHC analysis of 89 pairs of cancer and matched normal tissue showed that p21 expression was well correlated with NDRG1 expression." (PMID 31831018, 2019). "Further analysis demonstrated that NDRG1 was positively stained (+) in 59.6% (53/89) of normal tissues, whereas only 29.2% (26/89) of carcinoma cases were positive to NDRG1 stain (p < 0.0001)." (PMID 31831018, 2019). "NDRG1 demonstrated anti-oncogenic function and was proposed to be a metastasis suppressor in diverse type of cancers." (PMID 30042885, 2018). "N-myc downstream regulated gene 1 (NDRG1) is demonstrated as a tumor suppressor gene in several cancers." (PMID 29738439, 2018). "Collectively, these observations demonstrated that NDRG1 plays an important role in mediating the inhibition effects of DpdtC in HER2-overexpressed cancer cells via selective targeting of the HER2-ERK1/2 pathway." (PMID 29467385, 2018). "Previous studies of NDRG1 expression in cancer have been performed on cohorts of limited sizes, and have led to the conclusion that NDRG1 is a metastasis suppressor." (PMID 29898756, 2018). "NDRG1 mRNA expression in the 59 breast cell lines characterized by the Cancer Cell Line Encyclopedia (CCLE) was assessed." (PMID 29898756, 2018).
cancer (continued). "Collectively these studies demonstrated that NDRG1 functions as a metastatic suppressor that inhibits EMT in human cancer a key initial step in metastasis." (PMID 27894074, 2017). "Although the clinical status of NDRG1 in these cancers is well documented, the exact molecular function of NDRG1 had remained elusive." (PMID 28371345, 2017). "NDRG1 is generally reported to repress migration or metastasis, while MNKs promote migration of cancer cells such as MDA-MB-231." (PMID 28545025, 2017). "Given the potential link between SGK1, NDRG1 phosphorylation and cancer cell migration we used siRNA to deplete NDRG1 in MDA-MB-231 cells and then treated them with SGKi." (PMID 28545025, 2017). "Collectively, these findings demonstrated that pharmacological inhibition of LSD1 suppresses the mobility and invasiveness of cancer cells through up-regulation of NDRG1." (PMID 27894074, 2017). "In contrast, some studies have demonstrated that NDRG1 promotes cell migration and invasion in certain type of carcinoma." (PMID 28537875, 2017). "Iron chelators can induce the expression of NDRG1, a known metastatic suppressor, in a variety of human cancers." (PMID 26965928, 2016). "In support of these observations, cancer cells sensitive to BYL719 displayed decreased NDRG1 phosphorylation at T346 when treated with BYL719." (PMID 27451907, 2016). "Our results revealed a coamplification of the cancer and lipid transport related genes NDRG1 and LAPTM4B, as well as new genes potentially co-regulated and cooperating with LAPTM4B." (PMID 27711123, 2016). "Although, similar findings have been described in other cancers, this is the first study to show the implications of NDRG-1 expression in patients with PanNET." (PMID 26894863, 2016). "In summary, this investigation highlights a novel mechanism mediated by NDRG1 in inhibiting cancer cell migration." (PMID 25860930, 2015). "Recent studies demonstrated a novel mechanism through which NDRG1 plays a significant role in regulating cancer cell migration by inhibiting Src activity." (PMID 26431493, 2015). "One metastasis suppressor that has recently attracted increasing interest, due to its potent anti-cancer effects, is NDRG1." (PMID 26431493, 2015). "Considering the significant roles of both NDRG1 and Src in cancer metastasis, we recently conducted studies that explored the potential interplay of these two molecules." (PMID 26431493, 2015). "NDRG1 functions as a metastasis suppressor in various cancers and has been shown to be up-regulated in response to Fe chelator treatment in a variety of cell-types." (PMID 26335183, 2015). "Considering that the metastasis suppressor NDRG1 was found to up-regulate p21 expression in a wide variety of cancer cells, we further examined the levels of NDRG1 in response to the Fe chelators and DNA damaging agents in each of the five cell lines." (PMID 26335183, 2015). "N-myc Downstream Regulated Gene-1 (NDRG1) is a metastasis suppressor gene, and its implication in cancer progression and metastasis has been extensively studied." (PMID 26692161, 2015). "Considering different cancers possess markedly altered genetic backgrounds, all of our current experiments were performed with at least both cell-types in order to assess NDRG1 function." (PMID 25860930, 2015). "While NDRG1 is widely expressed and prominent in normal cells and tissues, its expression is significantly lower in various cancers, including breast, colon and prostate tumors, particularly in patients with bone or lymph node metastases." (PMID 26125440, 2015).